POU4F1 (POU class 4 homeobox 1)
Diseases named in the same sentence as POU4F1 in open-access papers (continued):
Sharing a sentence is not in itself a finding about the gene and the disease.
amblyopia (1 paper, 2025). Decreased vision that results from abnormal visual development. "Although our patient’s visual impairment was primarily attributed to anterior segment anomalies, the presence of nystagmus and amblyopia may also reflect underlying retinal circuitry deficits due to POU4F1 haploinsufficiency." (PMID 40978814, 2025).
autism spectrum disorder (1 paper, 2020). A spectrum of developmental disorders that includes autism, and Asperger syndrome. "Interestingly, alteration in the copy number of a region close to POU4F1/BRN3A is also associated with autism spectrum disorder." (PMID 32392208, 2020).
brain cancer (1 paper, 2025). A primary or metastatic malignant neoplasm affecting the brain. "Among the other transcription factors that we found among colon transcriptomics features Irx2, Pou4f1, Pou6f1, Tfap2a, Ctdp1, and Msx1 are known to be involved in neuronal development or closely related processes 31–37, and Fubp1 in brain cancer." (PMID 40791429, 2025).
deafness (1 paper, 2022). An inherited or acquired condition characterized by the complete loss of the ability to hear from one or both ears. "Genes already associated with hearing or deafness (mouse and/or zebrafish) were selected as controls/references for comparison and validation of the candidate genes’ results: Eya4 (DFNA10), Gsdmea (DFNA5), Gsdmeb (DFNA5), Pou4f1, Elavl4, Sclla3a, Gab1 (DFNB26), and Mettl1 (DFNM)." (PMID 36553541, 2022).
developmental delay (1 paper, 2025). "This case further supports the role of POU4F1 haploinsufficiency in both anterior segment dysgenesis and neuromotor developmental delay." (PMID 40978814, 2025). "This convergence of evidence strengthens the inclusion of POU4F1 in gene panels for syndromic developmental delay with ocular and neuromotor features." (PMID 40978814, 2025).
heart failure (1 paper, 2025). Inability of the heart to pump blood at an adequate rate to meet tissue metabolic requirements. "MR analysis identified significant causal associations between the genes implicated in BW loss (ADD3, HSPA12A, SLC18A2, PDZD8, DUSP5, CASP7) as well as EF% and LV volumes (GPC6, UGGT2, SLAIN1, POU4F1, MBNL2) in BXD mice post-DOX and heart failure (HF) outcomes in humans." (PMID 40321772, 2025).
small cell lung carcinoma (1 paper, 2020). Small cell lung cancer (SCLC) is a highly aggressive malignant neoplasm, accounting for 10-15% of lung cancer cases, characterized byrapid growth, and early metastasis. "POU4F1 was upregulated and induced neuroendocrine phenotype in small cell lung cancer." (PMID 32351322, 2020).
thyroid cancer (1 paper, 2021). "It was also found that the POU4F1 suppressed tumor metastasis via c-MET/STAT3 inhibition and EMT suppression in thyroid cancer." (PMID 34970597, 2021).
tumor (16 papers, 2010 to 2025). "In conclusion, we identified POU4F1 as a BLBC‐specific hyperactive TF, the expression of which is associated with tumor growth and metastasis, leading to poor clinical outcomes." (PMID 38491910, 2024). "POU4F1 expression was greater in COAD tumor tissues than in normal tissues in the TCGA-COAD dataset." (PMID 38962013, 2024). "POU4F1 is necessary for the tumor growth and malignant phenotypes of BLBC through regulating G1/S transition by direct binding at the promoter of CDK2 and CCND1." (PMID 38491910, 2024). "Taken together, these results demonstrated that POU4F1 was required for the tumor growth and the malignant phenotypes of BLBC, including proliferation, colony formation, migration and invasion." (PMID 38491910, 2024). "POU class 4 homeobox 1 (POU4F1), a stem cell-associated transcription factor, is considered to have tumor genetic function and promote tumor growth." (PMID 36176299, 2022). "Targeting POU4F1 not only inhibits tumor growth, but also conferring anti‐estrogen sensitivity." (PMID 38491910, 2024). "Additionally, tumor with higher expression of POU4F1 showed shorter disease‐free survival (DFS) in BLBC patients in the METABRIC, TCGA and SCAN‐B cohorts." (PMID 38491910, 2024). "However, knocking out POU4F1 in MDA‐MB‐231 xenografts not only inhibited tumor growth, but also enhanced the therapeutic response to tamoxifen treatment." (PMID 38491910, 2024). "Molecular profiling of tumor tissue or exosomes for neurotrophic factors (NGF, BDNF, GDNF), chemokines (CXCL12, CCL2), or neuronal transcription factors (POU4F1) may serve as predictive biomarkers of neural involvement." (PMID 41009819, 2025). "The results revealed that expression levels of SLCO4C1, POU4F1, DNASE1L2, WDR72, LPO, and C7 in tumor tissues were significantly higher than those in normal tissues, while the expression differences of SLC4A4, CELF4, and SLC11A1 were not statistically significant." (PMID 37745305, 2023). "When CDK2 and EZH2 was recovered in POU4F1‐KO BLBC cells, ERα was re‐expressed and the downstream signaling was re‐activated, resulting in the conversion between basal‐like and luminal‐like phenotype, suggesting the regulatory role of cell cycle in tumor cell identity." (PMID 38491910, 2024).
cancer (10 papers, 2010 to 2025). A tumor composed of atypical neoplastic, often pleomorphic cells that invade other tissues. "In our eight signature genes (ARL6IP4, ATP2A1, CRYAB, ELFN2, MAP2, MAT1A, ORC1, and POU4F1), prior research has elucidated the expression and function of several genes involved in the initiation and progression of cancer." (PMID 41567198, 2025). "Consistently, we observed significant hypomethylation in the proximal promoter of POU4F1 in carcinomas compared to BOTS, as well as in the first exon in hgOvCa in comparison with the remaining groups (GR file)." (PMID 39456618, 2024). "In this study, we found that TGF-β1 was able to trigger the expression of neuronal differentiation marker Tubb3 and neuron development transcription factor Pou4f1 in BMDMs, which was further promoted by the cancer cell–derived secretome in vitro." (PMID 36206343, 2022). "POU4F1 deletion substantially downregulated the MEK1/2 and ERK1/2 signalling pathways in cancer cells." (PMID 34178671, 2021). "POU4F1 is a member of the POU domain family of transcription factors and plays a key role in regulating cancers." (PMID 34178671, 2021). "For example, although MCC shows expression values contrary to the rest of skin states in the identified DEGs, there are genes like LGR5, POU4F1, SOSTDC1, KRT20 and MYO15A which are clearly postulated as differentiating genes in MCC diagnosing in comparison to other cancer-related skin states." (PMID 29750795, 2018). "For example, several genes from the final part of the ranking, present specific clear information on MCC against the rest skin states as LGR5, POU4F1, SOSTDC1, KRT20, TGM3 and MYO15A genes, as their gene expression levels are opposite against to the other cancer-related skin states." (PMID 29750795, 2018).
peripheral neuropathy (1 paper, 2025). A disorder affecting the peripheral nervous system. "In conclusion, our study describes a male patient with adolescent peripheral neuropathy carrying the heterozygous nonsense mutation POU4F1 NM_006237.4:c.55G>T(p.Glu19*) chr13:79177407." (PMID 41158507, 2025).
POU4F1 also shares sentences with these, for which no sentence is quoted: ocular hypertension (10 papers); diabetes (9); Hyperglycemia (3); infection (3); ischemia (3); neuroblastoma (3); Ewing sarcoma (2); inflammatory bowel disease (2); myopia (2); optic neuritis (2); retinal degeneration (2); adenocarcinoma (1); Ascites (1); benign ovarian tumors (1); benign tumors (1); cervical cancer (1); chronic pancreatitis (1); colon adenocarcinoma (1); colon cancer (1); cutaneous melanoma (1); glioblastoma (1); hepatocellular carcinoma (1); Hirschsprung disease (1); ischemic optic neuropathy (1); liver fibrosis (1); neurodevelopmental disorder (1); neuroendocrine tumors (1); nevus (1); Nystagmus (1); Optic neuropathy (1).
A further 14 diseases each share a sentence with POU4F1 in 1 paper.